GHET1 (gastric carcinoma proliferation enhancing transcript 1)
Synonyms: lncRNA-GHET1; GHET-1
Gene: Long non-coding RNA gene on chromosome 7 (148,987,527 to 148,989,432, forward strand). Ensembl gene ENSG00000281189.
Diseases named in the same sentence as GHET1 in open-access papers:
GHET1 is named in the same sentence as 34 diseases in open-access papers, as found by Europe PMC text mining. Sharing a sentence is not in itself a finding about the gene and the disease. The quoted sentences say what the papers report.
gastric cancer (21 papers, 2015 to 2023). A primary or metastatic malignant neoplasm involving the stomach. "In gastric cancer, GHET1 overexpression was also found to be associated with large tumor size, tumor invasion, and multidrug resistance." (PMID 30948501, 2019). "Another long non-coding RNA GHET1, which is highly expressed in gastric cancer cells, promotes the cell cycle regulators including CDK2 for inducing the invasive phenotype including the G1-to-S transition and the inhibition of p21." (PMID 36769170, 2023). "A long non-coding RNA, GHET1, is upregulated in gastric cancer, and its inhibition in gastric cancer cells leads to reductions in CDK2, Cyclin E1, CDK6, CDK4, and Cyclin D1." (PMID 36769170, 2023). "Gastric carcinoma high expressed transcript (GHET1) interacts with IGF2 mRNA binding protein 1 (IGF2BP1), which enhances the interaction between IGF2BP1 and c-Myc and increases the expression of c-Myc, thereby promoting cell proliferation." (PMID 35511773, 2022). "According to previous study, GHET1 interacted with IGF2BP1 to stabilize c-Myc mRNA so as to promote gastric cancer." (PMID 31682716, 2020). "In gastric cancer, the up-regulation of GHET1 promotes tumor cell proliferation in vitro and in vivo by physically binding to IGF2BP1, thereby enhancing the interaction between c-Myc mRNA and IGF2BP1; this can enhance the stability of c-Myc mRNA." (PMID 32280301, 2020). "Gastric carcinoma proliferation enhancing transcript 1 (GHET1) is a lncRNA suggested by several studies as an oncogene in cancers, such as breast cancer, colorectal cancer and gastric cancer." (PMID 31682716, 2020). "GHET1, located in chromosome 7q36.1, was firstly identified as an overexpressed lncRNA in gastric cancer." (PMID 32779318, 2020). "The relationship between lncRNA GHET1 and drug resistance has been studied in gastric cancer and other solid tumors." (PMID 32908508, 2020). "The lncRNA gastric cancer high expressed transcript 1 (GHET1) is located on chromosome 7q36.1 and was originally found to be highly expressed in gastric cancer." (PMID 32280301, 2020). "The prognostic value of GHET1 was investigated in seven kinds of human cancer in gastric cancer, lung cancer, hepatocellular carcinoma, breast cancer, esophageal squamous cell carcinoma, bladder cancer, and head and neck cancer." (PMID 30948501, 2019). "Originally, GHET1 was found to be overexpressed in gastric cancer and involved in gastric cancer cell proliferation in vitro and in vivo." (PMID 30948501, 2019). "Further mechanism study uncovered that GHET1 promoted the proliferation of gastric cancer cells via modulating the stability and expression of the oncogene c-Myc." (PMID 30988076, 2019). "GHET1 was first identified in gastric cancer, which was highly expressed in cancer tissues and promoted the proliferation of gastric cancer cells via modulating expression of c-Myc." (PMID 30988076, 2019). "In the clinical analyzing, compared with adjacent tissues, the GHET1 gene and protein expressions were significantly increased in the gastric cancer tissues." (PMID 30453964, 2018). "Their results demonstrated that GHET1 promoted gastric carcinoma cell proliferation, specifically increases the stability of c-Myc mRNA and up-regulates its expression." (PMID 30453964, 2018). "LncRNA GHET1 was found to be upregulated in gastric carcinoma tissues and correlate with poor prognosis, with a positive relationship with tumor size and invasion, and the shorter survival." (PMID 29954406, 2018). "In contrast, Yang and colleagues found that lncRNA GHET1 was significantly over-expressed in gastric cancer patients compared with healthy controls." (PMID 29113415, 2017). "A highly expressed long RNA in gastric cancer called gastric carcinoma high expressed transcript 1 (GHET1) also regulates c-Myc." (PMID 27129154, 2016). "Previous study has demonstrated in gastric cancer that GHET1 could interact with IGF2BP1, a member of IGF-2 binding proteins, to stabilize c-Myc mRNA." (PMID 31682716, 2020).
gastric cancer (continued). "Enhanced GHET1 expression can contribute to gastric carcinoma cell proliferation and tumor growth in vitro and in vivo by physically associating with IGF2BP1 and increasing the physical interaction of IGF2BP1 with c-Myc mRNA, consequently enhancing c-Myc mRNA stability and expression." (PMID 29954406, 2018). "Gastric carcinoma high expressed transcript 1 (GHET1), is a recently identified lncRNA, originally isolated in patients affected by gastric carcinoma, where it is upregulated; the high expression levels of this RNA are directly correlated with tumor size, tumor invasion and poor survival." (PMID 29165379, 2017). "Furthermore, the gastric carcinoma high expressed transcript 1 (GHET1) was downregulated in combined ACBP and ASLB treated cells compared with untreated control cells and ASLB-treated cells (4.9-fold and 3.6-fold, respectively, q < 0.05)." (PMID 29156779, 2017). "Knockdown of GHET1 was shown to inhibit proliferation rates of gastric carcinoma cells." (PMID 27077133, 2015). "Moreover, upregulation of GHET1 could be induced by hypoxia in gastric cancer cells, and the depletion of GHET1 c significantly enhanced the CpG island methylation of EGFR, which plays a crucial role in the metastasis of cancers." (PMID 32280301, 2020). "It has been reported that HOTAIR, ANRIL, GAPLINC, GHET1, H19, GAS5, and FENDRR, etc., play roles in the malignant progression of gastric cancer." (PMID 33744848, 2021). "Recent study identified a novel long noncoding RNA, named gastric carcinoma high expressed transcript 1 (GHET1), which was overexpressed in gastric cancer tissues and correlated with the worse prognosis of gastric cancer patients." (PMID 30988076, 2019). "Over-expression of GHET1 in MKN45 and AGS of gastric cancer cells significantly promotes cell proliferation in vitro." (PMID 29113415, 2017). "Further, GHET1 overexpression could prohibit cellular apoptosis by promoting the expression of Bcl-2 and could contribute to the development of multidrug resistance by promoting the expression of MDR1 and MRP1 in gastric cancer." (PMID 32280301, 2020). "Besides, there was a negative correlation between GHET1 expression and survival time in gastric cancer, breast cancer, esophageal squamous cell carcinoma, bladder cancer, and head and neck cancer." (PMID 30948501, 2019).
breast carcinoma (10 papers, 2019 to 2024). "There is a correlation between the high expression of GHET1 and the poor gemcitabine sensitivity in patients with breast cancer, and the knockdown of GHET1 is related with an increase in gemcitabine-induced cytotoxicity." (PMID 39512820, 2024). "Prior research in breast cancer indicates that PI3K/AKT pathway inhibition following lncRNA GHET1 knockdown reduces MCF-7 breast cancer cell growth and metastasis." (PMID 38213737, 2024). "GHET1 is a novel lncRNA that regulates the proliferation of breast cancer cells by decreasing HIF-1α expression by increasing the phosphorylation of LATS2 and YAP in order to inhibit the activation of the developmental Hippo pathway." (PMID 35626715, 2022). "Subsequently, the oncogenic role of GHET1 was suggested in lung cancer, hepatocellular carcinoma, breast cancer, colorectal cancer, esophageal squamous cell carcinoma, pancreatic cancer, bladder cancer, head and neck cancer, osteosarcoma, and glioma." (PMID 30948501, 2019). "Finally, it is worth mentioning that GHET1 lncRNA not only increase proliferation of breast cancer cells, but also increases glycolysis in them." (PMID 35626715, 2022). "Moreover, several studies showed that GHET1 was involved in regulating epithelial-mesenchymal transition process in hepatocellular carcinoma, breast cancer, colorectal cancer, esophageal squamous cell carcinoma, bladder cancer, and osteosarcoma." (PMID 30948501, 2019). "The overexpression of GHET1 was observed in most types of human cancer such as lung cancer, hepatocellular carcinoma, breast cancer, colorectal cancer, esophageal squamous cell carcinoma, pancreatic cancer, bladder cancer, head and neck cancer, osteosarcoma, and glioma." (PMID 30948501, 2019). "Additionally, several studies have reported that GHET1 can promote EMT in esophageal squamous cell carcinoma, breast cancer, colorectal cancer, osteosarcoma, renal cell carcinoma, and bladder cancer." (PMID 32280301, 2020).
colorectal cancer (9 papers, 2018 to 2021). A primary or metastatic malignant neoplasm that affects the colon or rectum. "In addition, lncRNA GHET1 silencing attenuated the proliferation and invasion of colorectal cancer cells." (PMID 34372865, 2021). "Knockdown of lncRNA GHET1 could also suppress the proliferation and metastasis of colorectal cancer cells." (PMID 34372865, 2021). "For instance, lincRNA DQ786243 contributed to proliferation and metastasis of colorectal cancer both in vitro and in vivo; GHET1 and TUG1 promoted colon cancer progression; GAS5 contributed to lymphatic metastasis in colorectal cancer; Linc00152 and LincRNA-ROR hold prognostic value." (PMID 31497531, 2019). "Previous studies have demonstrated that lncRNA PCGM1, GHET1, CCAT1-L, and PVT1 regulate Myc transcription or RNA and protein stability in the prostate, gastric, and colorectal cancers." (PMID 34696771, 2021).
cervical cancer (7 papers, 2019 to 2021). A primary or metastatic malignant neoplasm involving the cervix. "The loss-of-function study indicated knockdown of GHET1 expression markedly inhibits cervical cancer cell proliferation, migration, and invasion." (PMID 30948501, 2019). "In conclusion, GHET1 expression is significantly increased in cervical cancer tissues and cells, and associated with clinical progression and poor prognosis in patients with cervical cancer." (PMID 30948501, 2019). "Moreover, we found high expression of GHET1 was associated with advanced clinical stage, lymph node metastasis, distant metastasis, and poor histological grade in cervical cancer patients." (PMID 30948501, 2019). "Furthermore, we investigated the diagnostic and clinical significance of GHET1 in cervical cancer." (PMID 30948501, 2019). "Then, we found high expression of GHET1 is a useful biomarker to discriminate cervical cancer tissues from non-tumorous tissues, and associated with advanced clinical stage, lymph node metastasis, distant metastasis and poor histological grade in cervical cancer patients." (PMID 30948501, 2019). "It has also been demonstrated that high levels of long non-coding RNA (lncRNA) gastric carcinoma high expressed transcript 1 (GHET1) can also promote the development of cervical cancer via activating the Wnt/β-catenin pathway." (PMID 34372865, 2021). "In cervical cancer, gastric carcinoma proliferation enhancing transcript 1 (GHET1) regulates AKT/mTOR and Wnt/β-catenin signaling pathways by stabilizing the interaction of E2F6 and IGF2BP2." (PMID 32391379, 2020). "Present study planned to investigate the function of GHET1 in cervical cancer and its mechanism in regulating AKT/mTOR and Wnt/β-catenin signaling pathways." (PMID 31682716, 2020). "We executed CCK-8 assay to assess the influence of GHET1 on cell proliferation and found that proliferation activity was obviously suppressed in cervical cancer cells transfected with si-GHET1 (P<0.001)." (PMID 30948501, 2019). "In our study, we found GHET1 expression was markedly elevated in cervical cancer tissue specimens and cell lines compared with adjacent normal cervical tissue specimens and human normal cervical cell line, respectively." (PMID 30948501, 2019). "In our study, we also found that GHET1 expression was markedly elevated in cervical cancer tissue specimens and cell lines compared with adjacent normal cervical tissue specimens and human normal cervical cell line, respectively." (PMID 30948501, 2019). "Because GHET1 expression was relative high in HeLa and CaSki cells amongst four cervical cancer cell lines, we chose HeLa and CaSki cells for following loss-of-function study." (PMID 30948501, 2019). "In our results, we preliminarily found that knockdown of GHET1 expression markedly inhibited cell proliferation, migration, and invasion in cervical cancer, which was consistent with its function in other cancers." (PMID 30948501, 2019). "In our future research, we will further explore the biological function and molecular mechanism about GHET1 in cervical cancer." (PMID 30948501, 2019). "Based on the clinical results about GHET1 in cervical cancer, we guessed that GHET1 also functions as oncogenic lncRNA to regulate tumor cell proliferation, migration, and invasion in cervical cancer, like it in other cancers." (PMID 30948501, 2019). "The survival analysis showed high GHET1 expression was an independent unfavorable prognostic factor in cervical cancer patients." (PMID 30948501, 2019). "We observed that GHET1 expression was markedly elevated in cervical cancer tissue specimens compared with adjacent normal cervical tissue specimens (P<0.001)." (PMID 30948501, 2019). "Knockdown of GHET1 expression markedly inhibits cervical cancer cell proliferation, migration, and invasion." (PMID 30948501, 2019).
cervical cancer (continued). "Then, high GHET1 expression was identified as an independent unfavorable prognostic factor in cervical cancer patients through multivariate Cox regression analysis (P=0.001)." (PMID 30948501, 2019). "A previous study demonstrated that lncRNA GHET1 could affect the development of cervical cancer via modulating the Wnt/β-catenin signaling pathway." (PMID 34372865, 2021). "Another therapeutic opportunity could be to reduce long non-coding RNA oncogenes such as gastric carcinoma proliferation enhancing transcript 1 (GHET1), which has been shown to activate both mTOR and Wnt/β-catenin pathways in cervical cancer." (PMID 33668092, 2021). "lncRNA GHET1 has been proved that it could promote osteosarcoma and cervical cancer development and progression via Wnt/β-catenin signaling pathway, and WNT might be an important marker for targeted cancer therapy." (PMID 32908508, 2020). "The relationship between GHET1 expression and prognosis in cervical cancer patient was still unknown." (PMID 30948501, 2019). "In addition, we also observed that GHET1 expression in four cervical cancer cell lines (SiHa, C-33A, HeLa, and CaSki) was obviously increased in comparison with human normal cervical cell line (Ect1/E6E7) (P<0.001)." (PMID 30948501, 2019). "In conclusion, GHET1 acts as an oncogenic lncRNA in cervical cancer." (PMID 30948501, 2019). "Moreover, transwell migration and invasion assays were performed to estimate the effect of GHET1 on cervical cancer cell migration and invasion." (PMID 30948501, 2019). "Furthermore, we analyzed the correlations between GHET1 expression and clinicopathological parameters for estimating the clinical value of GHET1 in cervical cancer patients." (PMID 30948501, 2019). "Due to high levels of GHET1 in cervical cancer tissues and cells, GHET1 might be a useful marker to identify cervical cancer tissues from non-tumorous tissues." (PMID 30948501, 2019). "Additionally, lncRNA GHET1 could accelerate the development of cervical cancer via modulating the AKT/mTOR and Wnt/β-catenin signaling pathways." (PMID 34372865, 2021). "Interestingly, the expression of lncRNA GHET1 could also promote the progression of cervical cancer via activating the Wnt/β-catenin pathway." (PMID 34372865, 2021). "Therefore, we measured the GHET1 expression in cervical cancer tissue samples and analyzed the relationship between GHET1 expression and clinicopathological characteristics for estimating the clinical significance of GHET1 in cervical cancer." (PMID 30948501, 2019). "In conclusion, we revealed that down-regulation of GHET1 suppresses cervical cancer progression through regulating AKT/mTOR and Wnt/β-catenin signaling pathways, indicating GHET1 as a promising molecular biomarker for CC treatment improvement." (PMID 31682716, 2020). "However, the biological function of GHET1 was still unknown in cervical cancer." (PMID 30948501, 2019). "However, the role of GHET1 remained unknown in cervical cancer." (PMID 30948501, 2019). "Although both AKT/mTOR and Wnt/β-catenin pathways have been investigated in cervical cancer respectively, no studies have been reported on the regulation of these pathways by GHET1 in CC." (PMID 31682716, 2020). "We drew ROC curve and found that GHET1 is a useful biomarker to discriminate cervical cancer tissues from non-tumorous tissues." (PMID 30948501, 2019). "However, the clinical significance of GHET1 and the related biological function in cervical cancer have not been reported at present." (PMID 30948501, 2019). "However, the role of GHET1 has not been explored in cervical cancer." (PMID 31682716, 2020). "However, there was no report about the expression of GHET1 in cervical cancer." (PMID 30948501, 2019).
osteosarcoma (7 papers, 2019 to 2024). A usually aggressive malignant bone-forming mesenchymal neoplasm, predominantly affecting adolescents and young adults. "For example, when cell lines from osteosarcomas are contrasted with benign osteoblastic cells, the expression of the lncRNA gastric carcinoma proliferation enhancing transcript 1 (GHET1) is amplified." (PMID 39015175, 2024). "Knockdown of GHET1, one of the lncRNAs upregulated in osteosarcoma, by naked siRNA improved tumor growth and metastasis in vivo." (PMID 36293439, 2022). "GHET1 knockdown was reported to inhibit osteosarcoma cell migration, invasion and EMT, at least in part via regulation of Wnt/β-catenin pathway." (PMID 34130697, 2021). "Gastric carcinoma proliferation enhancing transcript 1 (GHET1) is an upregulated lncRNA in osteosarcoma cell lines in comparison with normal osteoblastic cells." (PMID 34130697, 2021). "Additionally, GHET1 expression was also suggested to be related with clinical progression in pancreatic cancer and osteosarcoma." (PMID 30948501, 2019).
hepatocellular carcinoma (6 papers, 2019 to 2022). A malignant tumor that arises from hepatocytes. "For example, lncRNA GHET1 indicates poor prognosis and facilitates cell proliferation through silencing KLF2 expression in hepatocellular carcinoma." (PMID 33109776, 2020). "LncRNA GHET1 is activated by histone 3 lysine 27 (H3K27) acetylation and promotes hepatocellular carcinoma (HCC) tumorigenesis through regulating activating transcription factor 1 (ATF1)." (PMID 31885739, 2019).
bladder cancer (4 papers, 2015 to 2020). "Gastric carcinoma proliferation enhancing transcript 1 (GHET1) is an unspliced lncRNA transcribed from chromosome 7 that has been implicated in gastric and bladder cancers." (PMID 27077133, 2015). "The finding in bladder cancer suggested that GHET1 acted as an oncogene via promoting the EMT of the cells." (PMID 30988076, 2019). "Additionally, GHET1 was also found overexpressed in bladder cancer cell lines and tissues." (PMID 30988076, 2019).
glioma (4 papers, 2019 to 2021). A benign or malignant brain and spinal cord tumor that arises from glial cells (astrocytes, oligodendrocytes, ependymal cells). "Very recently, emerging studies indicated that lncRNA DANCR and GHET1 were sponges of miR-216a in glioma cells in regulating cell progression and angiogenesis." (PMID 33817241, 2020).